SHBG (sex hormone binding globulin)
Diseases named in the same sentence as SHBG in open-access papers (continued):
Sharing a sentence is not in itself a finding about the gene and the disease.
Obesity (continued). "The mean cellular volume, serum phosphate, albumin, creatinine, HDL-cholesterol, amylase, lipase, iron, and SHBG levels were significantly lower among patients with obesity." (PMID 40463745, 2025). "SHBG showed an inverse trend in the smoothed curves with the obesity-related indicators, and was significantly negatively correlated with 16 indicators at the 1 st, and 2nd tertile levels in both models (P < 0.05)." (PMID 41310874, 2025). "For example, SHBG levels are negatively correlated with markers of hepatic de novo lipogenesis (DNL), indicating that enhanced lipogenesis contributes to reduced SHBG synthesis and release, especially in individuals with obesity and hepatic steatosis." (PMID 40625923, 2025). "This study aims to investigate the relationship between metabolic dysfunction-associated fatty liver disease (MAFLD) and sex hormones and sex hormone-binding globulin (SHBG) in boys with obesity." (PMID 39980852, 2025). "Estrogen also amplifies mTOR outputs via IGF-1R upregulation, sustaining proliferative/survival programs that are accentuated in obesity-related endocrine milieus (increased aromatization, reduced SHBG)." (PMID 41301707, 2025). "In males with conditions that alter SHBG, including obesity, aging, HIV, use of anticonvulsants, and liver cirrhosis/hepatitis, which represented a third of our study population, calculating free testosterone concentrations is recommended." (PMID 40697882, 2025). "In females, estradiol and SHBG mitigated obesity-related markers, whereas testosterone and FAI displayed inconsistent or inverted U-shaped trends." (PMID 41310874, 2025). "Low circulating levels of SHBG represent a promising biomarker for obesity-related metabolic dysfunctions beginning in childhood." (PMID 40863113, 2025). "SHBG plays a crucial role in transporting sex hormones and regulating their bioavailability and has been found to correlate inversely with obesity and IR, two key components of MetS." (PMID 40863113, 2025). "Studies further indicate an independent role of SHBG in obesity and metabolic diseases, but the mechanisms remain largely unresolved." (PMID 40532849, 2025). "In the horizontal pleiotropy analysis, we found that the effects of SHBG levels on obesity, BMI, and waist circumference, and the effects of age at menarche on childhood obesity, had horizontal pleiotropy (p < 0.05)." (PMID 41427029, 2025). "Women diagnosed with PCOS having reduced sex hormone-binding globulin (SHBG) levels are more prone to obesity, IR, T2D, hyperandrogenism, and cardiovascular disease (CVD), primarily owing to prevailing IR." (PMID 40650016, 2025). "Measuring free testosterone has certain advantages over total testosterone because it is less affected by sex hormone-binding globulin changes that occur in obesity, diabetes, and liver dysfunction." (PMID 41464795, 2025). "In adolescents with PCOS, decreased SHBG levels are a concerning indicator of high NAFLD risk, exacerbated by obesity and metabolic disorders." (PMID 40625923, 2025). "As males with obesity or diabetes often suffer from low testosterone and SHBG levels, the data suggests that further investigation into the effects of calorie-restricted KD on male testosterone and SHBG levels is a promising area for additional research." (PMID 40535039, 2025). "There is compelling evidence that supports SHBG’s involvement in glucose and lipid metabolism and its role as a biomarker for obesity-related disorders including T2D." (PMID 41180177, 2025). "In contrast to previous epidemiologic data suggesting that SHBG is more strongly associated with metabolic risk in men than T or FT is, we found a much weaker link between SHBG and the metabolic phenotype of severe obesity in males (BMI > 35 kg/m2)." (PMID 39885510, 2025).
Obesity (continued). "In contrast, overweight, obesity, increased lipogenesis, and hepatic steatosis exacerbate SHBG synthesis inhibitory factors (e.g., chicken ovalbumin upstream promoter transcription factor (COUP-TF) or peroxisome proliferator-activated receptor gamma (PPARγ))." (PMID 40427034, 2025). "Accordingly, men with low levels of SHBG (e.g., obesity) tend to have lower total testosterone levels whereas those with high levels of SHBG (e.g., hyperthyroidism) have a high total testosterone level." (PMID 40863113, 2025). "Prepregnancy obesity, childhood adiposity, hormonal changes in adiponectin, SHBG, estradiol, and testosterone, placental involvement, and genetic predisposition were the identified mechanisms linking the two conditions." (PMID 38498127, 2024). "Metformin has shown positive effects on ovulation in patients with PCOS, reducing LH levels, free LH, free radicals, FSH, and sex hormone-binding globulin (SHBG) in women with obesity and PCOS." (PMID 38737668, 2024). "This likely led to overdiagnosis, as obesity generally inhibits the insulin-mediated hepatic release of SHBG, resulting in its reduction." (PMID 39085709, 2024). "The purpose of this work was to find a link between the breast cancer (BC)-risk effects of sex hormone-binding globulin (SHBG)-associated polymorphisms and obesity." (PMID 38672173, 2024). "The excess adipose tissue in obesity induces hormonal perturbations, in particular escalating estrogen levels and decreasing sex hormone-binding globulin (SHBG), which can lead to menstrual irregularities and anovulation." (PMID 39280012, 2024). "The result was attributed to prepregnancy obesity, low levels of sex hormone-binding globulin (SHBG) and high levels of androgens and estrogens, which predispose to earlier menarche." (PMID 38498127, 2024). "Concerning sex steroid hormones, TT and SHBG emerged as protective factors for obesity status (OR = 0.997; OR = 0.977), with only estradiol identified as a risk factor (OR = 1.008)." (PMID 38524635, 2024). "We observed an altered reproductive hormone profile, characterized by higher levels of oestradiol, LH, and FAI, and lower levels of SHBG in sons born of mothers with pre-pregnancy overweight and obesity." (PMID 37935951, 2024). "We also stratified the mediation analysis by BMI categories, given the robust evidence linking overweight and obesity to altered SHBG levels." (PMID 38954350, 2024). "Body fat distribution and adipocyte differentiation were influenced greatly by sex hormones, and both sex hormones and sex hormone-binding globulin were found to have a strong correlation with obesity." (PMID 39063564, 2024). "Obesity, at any age, can lower the plasma level of the sex hormone-binding globulin (SHBG), which raises the level of free testosterone and the inflammatory cytokines that cause acne." (PMID 38255795, 2024). "Individuals with obesity exhibit lower levels of TT and SHBG, accompanied by elevated estradiol levels." (PMID 38524635, 2024). "Men with T2D and obesity often show reduced total and free testosterone levels and lower SHBG levels." (PMID 38892561, 2024). "One of the major factors that influence SHBG levels is high body mass index, or obesity, and even though we adjusted for this in our analysis, we cannot rule out residual confounding." (PMID 37369886, 2024). "Serum levels of total testosterone and sex hormone-binding globulin were significantly lower in men with obesity and DM compared with the control." (PMID 37208686, 2023). "Secondly, low total testosterone and sex hormone-binding globulin levels in men correlate with hyperinsulinism and elevated inflammatory cytokines that accompany obesity and an increased waist circumference." (PMID 37239168, 2023). "Men with obesity present an impaired reproductive hormonal profile, with lower serum levels of the sex hormone-binding globulin (SHBG) and testosterone." (PMID 38068717, 2023).
Obesity (continued). "On the other hand, obesity can inhibit the synthesis of SHBG in the liver, thus promoting the secretion of androgen and insulin, which leads to IR, while high levels of insulin and androgen further aggravate the abnormal fat distribution." (PMID 36967808, 2023). "The most common causes of the constellation of a low serum total testosterone, low serum SHBG, and normal free serum testosterone (ie, pseudohypogonadism) are obesity and T2D." (PMID 36995891, 2023). "Increases in TT and FAI levels were observed in PCOS patients with obesity, with a simultaneous decline in SHBG levels in our study." (PMID 37720537, 2023). "In conclusion, sex hormones mediated the effects of overweight/obesity on diabetes, especially SHBG and FSH." (PMID 36767197, 2023). "Sex-hormone-binding globulin correlated inversely with BMI, HgBA1, bioavailable T, and free T values and with subjective complaints of obesity and weight gain." (PMID 36766605, 2023). "In those women, lower concentrations of SHBG were detected, when compared to their age- and weight-matched counterparts with peripheral or gluteal excess weight or obesity." (PMID 36836575, 2023). "In patients with PCOS, obesity and hyperinsulinemia are accompanied by a decrease in SHBG levels, and testosterone, predominantly in the free form unbound to SHBG, increases." (PMID 37895341, 2023). "In current study, we showed that PCOS women with EH have evidence of advanced age, obesity, prolonged menstrual cycle, decreased SHBG, and dyslipidemia, compared with PCOS women with normal endometrium." (PMID 37149578, 2023). "Free serum sex hormones, eg. estrogen and testosterone, are is increased in obesity in part due to a decrease in the sex hormone-binding globulin (SHBG)." (PMID 36909335, 2023). "Serum SHBG level is dependent on its glycosylation status, and a number of recent studies have shown serum SHBG correlation with obesity, type 2 diabetes, and other endocrine disorders, which makes it an interesting biomolecule from a diagnostic perspective." (PMID 37402098, 2023). "Firstly, VPA-induced obesity and hyperinsulinemia can inhibit the synthesis of sex hormone binding globulin and, consequently, the levels of circulating testosterone." (PMID 37239168, 2023). "This subgroup was characterized by a significantly more frequent occurrence of overweight and obesity diagnosed based on BMI values, according to the Word Health Organization criteria, compared to the subgroup with normal SHBG levels." (PMID 36968815, 2023). "SHBG systemic level has been shown to be decreased in patients with obesity, type 2 diabetes (T2DM), and in patients with metabolic syndrome (MetS)." (PMID 37697311, 2023). "Reasonably modulating BioT and estradiol, especially SHBG, facilitated the attenuation of the harmful effects of obesity on male health." (PMID 37483981, 2023). "Using MR Analysis, we found independent effects of type 2 diabetes, fasting insulin, and HbA1c on total testosterone and sex hormone-binding globulin after maximum exclusion of the effects of obesity, BMI, TG, LDL and Adiponectin." (PMID 37900148, 2023). "As expected, the median SHBG level was the lowest in the subgroup with obesity and the highest in the normal weight subgroup." (PMID 35140785, 2022). "Over 60% of sex hormones bind to SHBG, which increases inversely with obesity or hyperinsulinemia; the opposite is true in the case of aging." (PMID 36014851, 2022). "We next examined if the sex-specific differences in IL-10 regulation by obesity and T2D associated with the levels of circulating hormones linked to the gonadotropin axis (FSH, LH, SHBG, E1 and E2)." (PMID 36313784, 2022). "The reverse was not the case, and the effect was only partially dependent on an obesity related decrease in SHBG." (PMID 35834069, 2022). "Obesity also reduces the sequestration of estrogen by downregulating levels of sex hormone-binding globulin, leading to increased circulating unbound estrogen." (PMID 35326592, 2022).
Obesity (continued). "Studies have demonstrated that obesity decreases the expression of sex hormone-binding globulin (SHBG), which results in higher levels of estradiol in the blood." (PMID 36551694, 2022). "exanimated the role of obesity-related factors including CRP, hemoglobin-A1c (HbA1c), sex hormone-binding globulin (SHBG), and testosterone in the association of adiposity and CRC risk." (PMID 36407320, 2022). "Our results suggest that intermittent fasting decreases androgen markers (i.e., testosterone and the free androgen index (FAI)) while increasing sex hormone-binding globulin (SHBG) levels in premenopausal females with obesity." (PMID 35684143, 2022). "Only 1–2% is free and bio-active, and this amount is highly dependent on SHBG levels and any circumstance which affects SHBG levels like estrogen levels, hyperinsulinemia, obesity, and liver conditions." (PMID 36140452, 2022). "In our study, a high exposure to the MEP metabolite of DEP was one of the most prominent factors for low SHBG levels and obesity." (PMID 36149653, 2022). "Obesity is accompanied by metabolic changes that decrease androgens and sex hormone-binding globulin (SHBG), thereby increasing the availability of estrogens." (PMID 35885460, 2022). "Sex hormone-binding globulin (SHBG) levels are low in adult subjects with obesity when compared to normal-weight individuals." (PMID 33689083, 2021). "This characteristic hormonal pattern in obesity and type 2 diabetes – low blood testosterone and SHBG with normal LH and FSH - is better termed pseudo-hypogonadism." (PMID 35116001, 2021). "Low plasma SHBG levels have been also found in children with obesity; however, the reasons for such reduction need to be yet determined." (PMID 33689083, 2021). "It is important to mention that low plasma SHBG levels are found in children with obesity; this is in agreement with our results showing that prepubertal children with obesity had half the plasma SHBG levels present in normal-weight prepubertal children." (PMID 33689083, 2021). "Fatty liver is linked to obesity and it appears that the combination of these two conditions is related to low testosterone in a significant percentage of men, partly due to decreased SHBG levels that frequently accompanies obesity and NAFLD12." (PMID 34244582, 2021). "Individuals with obesity are commonly characterized by low serum sex hormone binding globulin (SHBG) levels." (PMID 33715205, 2021). "The primary impact in lowering blood testosterone in obesity is through a reduction of blood SHBG, the carrier protein for the majority of circulating testosterone." (PMID 35116001, 2021). "Of note, it is likely that factors other than DNL, such as tumour necrosis factor α and interleukin 1β, also contribute to the decreased serum SHBG levels in obesity and related disorders." (PMID 33715205, 2021). "Whereas obesity is related to secondary hypogonadism, high SHBG levels, related to liver fibrosis degree and HCV co-infection, are responsible for compensated forms." (PMID 33515211, 2021). "For this purpose, we determined several morphometric and biochemical parameters in normal-weight and prepubertal children with obesity, as well as quantified plasma SHBG, TNFα receptor 1 (TNFα-R1), and adiponectin levels." (PMID 33689083, 2021). "Obesity has been shown to trigger a reduction in sex hormone-binding globulin (SHBG) and consequentially an increase in the bioavailability of estrogen." (PMID 34319018, 2021). "Our results showed that prepubertal children with obesity had decreased plasma SHBG levels compared to normal-weight controls (67 nmol/L vs 172 nmol/L)." (PMID 33689083, 2021). "Together with reduced production of sex hormone binding globulin due to obesity, this leads to increased levels of circulating bioavailable estrogens." (PMID 33128203, 2021).
Obesity (continued). "This is of importance since we have reported that alterations in proinflammatory and anti-inflammatory cytokines occurring in obesity play an important role in regulating hepatic SHBG production." (PMID 33689083, 2021). "Girls with obesity had increased testosterone levels from 8 years onwards resulting in relative hyperandrogenism, particularly when the lower SHBG levels in obesity are considered." (PMID 34386750, 2021). "In conclusion, the results obtained in this study show that prepubertal children with obesity had decreased plasma SHBG levels compared to normal-weight controls." (PMID 33689083, 2021). "More importantly, this SHBG correlation with adiponectin was also found when analyzing only subjects with obesity." (PMID 33689083, 2021). "It is well-known that adult individuals with obesity show lower plasma sex hormone-binding globulin (SHBG) levels than normal-weight subjects." (PMID 33689083, 2021). "Nevertheless, we found strong correlations between SHBG and insulin plasma levels when analyzing our study population or children with obesity alone." (PMID 33689083, 2021). "In specific cases (such as obesity, chronic liver disease, or total testosterone levels in the borderline range), sex-hormone binding globulin (SHBG) should be measured and free testosterone calculated." (PMID 32486230, 2020). "We demonstrate strong correlations in women with PCOS between SHBG and components of MetS, like obesity, lipid profile, IR and preDM, and that is in line with the studies performed both in PCOS women and the general population." (PMID 33092301, 2020). "As the degree of obesity increases, peripheral aromatization of androgens to estrogens improves, while liver synthesis of sex hormone-binding globulin (SHBG) decreases, which will result in increased levels of free estradiol and testosterone." (PMID 33343510, 2020). "Decreased concentrations of SHBG in obesity thus result in a greater percentage of free testosterone and a condition of relative functional hyperandrogenemia." (PMID 32535783, 2020). "For both men and women, disrupted levels of reproductive hormones, such as sex hormone binding globulin (SHBG), follicle-stimulating hormone (FSH), and testosterone have also been linked to obesity, resulting in infertility." (PMID 32500010, 2020). "Due to this relationship between SHBG and TT levels with obesity, FT levels, which have been related to hypogonadism symptoms, would be a suitable variable to diagnose the hypogonadism in obese subjects." (PMID 31370189, 2019). "On the other hand, interestingly, db/db mice overexpressing human SHBG reportedly show resistance to the development of obesity and hepatosteatosis." (PMID 30046278, 2018). "As such, obesity-related reduced SHBG levels and increased production of estrogen and testosterone can lead to greater free/bioactive estrogen and testosterone levels." (PMID 29713614, 2018). "Regarding the effect of obesity on male reproductive hormones, serum cFT concentrations were decreased, and serum SHBG levels were increased (P < 0.05) in the obesity group." (PMID 29769123, 2018). "Hepatic SHBG production is negatively influenced by hyperinsulinemia, which is more prevalent in obesity." (PMID 29973985, 2018). "Multivariate linear models of SHBG as dependent variable in pregnant women according to obesity status." (PMID 30321217, 2018). "Sex hormone-binding globulin (SHBG) is a serum protein released mainly by the liver, and a low serum level correlates with a risk for metabolic syndrome including diabetes, obesity, and cardiovascular events." (PMID 30046278, 2018). "Beyond this gradual increase, reduced SHBG levels largely reflects obesity, particularly men with a substantial or predominant visceral component with associated metabolic consequences." (PMID 29995902, 2018).